CD47 (CD47 molecule)
Diseases named in the same sentence as CD47 in open-access papers (continued):
Sharing a sentence is not in itself a finding about the gene and the disease.
tumor (continued). "However, on the other hand, chemotherapy may increase the release of tumor antigen and DNA from dying tumor cells, which may synergize with CD47 blockade." (PMID 28077173, 2017). "Therefore, with the modular design strategy, we have successfully engineered both phosphatase- and kinase-based iSNAPs capable of sensing, rewiring the ‘don’t eat me’ CD47 signaling and reprogramming macrophages for enhanced phagocytic activities against opsonized tumor cells." (PMID 28883531, 2017). "Moreover, by combining the recruitment and activation of FcRs via the antibody Fc domain and the blockade of CD47-SIRPα interaction by the endogenous low affinity CD47-antagonistic SIRPα domain, licMAB molecules significantly enhanced phagocytosis of tumor cells." (PMID 28061465, 2017). "Therefore, proper combination therapy of chemotherapeutic drugs and anti-CD47 antibody may depend on the type, timing, dose of these agents, and tumor types." (PMID 28077173, 2017). "However, tumour cells escape macrophage killing through the upregulation of the ‘don't eat me’ signal CD47, which is a ‘self’ integrin-associated protein expressed by healthy cells which binds to the signal regulatory protein α (SIRPα) on macrophage cell surfaces to inhibit phagocytosis." (PMID 28404796, 2017). "Although blocking the interaction between CD47 on tumor cells and SIRPα on the host macrophages and DCs induces antitumor immune responses, simultaneous interruption of the TSP1-CD47 signaling in tumor stromal cells, such as endothelial cells, may potentially facilitate tumor progression." (PMID 27283989, 2017). "Thus, regional intra-tumor delivery of CD47-CAR-T cells is a feasible approach in clinic." (PMID 29065481, 2017). "Consequently, the binding properties of licMABs enable them to selectively bind to CD33-expressing tumor cells in the presence of excess of RBCs expressing CD47, thus overcoming the antigen sink that RBCs may represent." (PMID 28061465, 2017). "Our results indicate that although treatment with antibody against CD47 induces antitumor immune responses by blocking the inhibitory CD47-SIRPα signaling, this treatment may also potentially promote tumor progression by blocking CD47 signaling in tumor stromal endothelial cells." (PMID 27283989, 2017). "KAIMRC1 cells were also strongly positive for CD47 which suggests that these cells might have tumor invasion and metastasis capability Enhanced expression of CD47, a transmembrane glycoprotein mediating a ‘don’t eat me’ signal, has been reported in various cancers." (PMID 29187162, 2017). "Therefore, either type might promote the delay in tumor growth stimulated by tumor resection alone or in combination with anti-CD47 treatment." (PMID 28076333, 2017). "However, it remains unclear as to whether and how administration of anti-CD47 antibody may affect tumor progression via its potential role in the regulation of angiogenesis." (PMID 27283989, 2017). "In this review, we highlight the various functions of CD47, discuss anti-tumor responses generated by both the innate and adaptive immune systems as a consequence of administering anti-CD47 blocking antibody, and finally elaborate on the clinical potential of CD47 blockade." (PMID 28077173, 2017). "Thus, CD47 is a checkpoint molecule for both innate and adaptive immunity for tumor evasion." (PMID 28077173, 2017). "Tumor-targeting antibodies may be conjugated with anti-CD47 or SIRPα-Ig to increase specificity." (PMID 28077173, 2017). "These cytokines were all found to be significantly upregulated in the debulking tumor + CD47 antibody group and may therefore provide a molecular explanation for the increased infiltration of macrophages into recurrent tumor as well as antibody stimulated antitumor activity in these macrophages." (PMID 28076333, 2017).
tumor (continued). "Notably, this molecule would be smaller in size than the licMAB, which could be beneficial when transferring the CD47-SIRPα blockade to solid tumors, as tumor penetration appears to be a challenging issue." (PMID 28061465, 2017). "Hence, disruption of the CD47-SIRPα interaction might represent a therapeutic strategy in AML to induce clearance of tumor cells." (PMID 28061465, 2017). "Those prophagocytic signals on tumor cells may provide a therapeutic window to treatment with anti-CD47 antibodies without causing phagocytosis of normal cells that lack these “eat me” signals." (PMID 28484448, 2017). "Therefore, the antitumor effect obtained in the xenograft model may be mediated majorly by anti-CD47 antibody targeting ESA+ CD133− tumor cells." (PMID 28484448, 2017). "Furthermore, cells expressing CD47, such as RBCs, might function as an antigen sink and could prevent CD47-targeting molecules from binding to tumor cells in vivo." (PMID 28061465, 2017). "Furthermore, we found that the downregulation of CD47 in NSCLC cells in vivo significantly inhibited tumor growth and metastasis; suggesting that CD47 critically controls tumor cell growth and metastasis in vivo, and supporting the therapeutic potential of targeting CD47 for NSCLC treatment." (PMID 27411490, 2016). "Therefore, we tested whether Cdc42 may also be a downstream mediator of CD47-induced tumor invasion in NSCLC." (PMID 27411490, 2016). "One might speculate that there is a resulting reprogramming of TAMs, including microglia, toward the M1 phenotype, although it is also possible that anti-CD47 blocking antibodies provided selective environments in the tumor that favor pre-committed M1 macrophages to enter and/or proliferate." (PMID 27092773, 2016). "Interestingly, CD47 blockage increased the macrophage phagocytosis of tumor cells, indicating that this could be an effective immunotherapeutic approach." (PMID 28115942, 2016). "Additionally, studies have shown that ligation of CD47 could induce apoptosis of cancer cells and modulate tumor microenvironment." (PMID 27863402, 2016). "A comparison of gene expression altered by B6H12 in bCSC in vitro with gene expression significantly correlated with CD47 mRNA expression in the TCGA TNBC primary tumor data was used to identify additional potential targets of CD47 signaling in TNBC that could be regulated by B6H12." (PMID 26840086, 2016). "As pre-clinical data suggests that high circulating TSP-1 levels produced by tumor stroma may indirectly increase tumor perfusion while decreasing peritumoral and systemic blood flow, CD47-targeting mAbs are therefore likely to counteract these effects through regional stimulation of NO signaling." (PMID 26578962, 2015). "In addition, CD47:SIRPα interaction may also indirectly promote tumor dissemination through binding of tumor cells to macrophages that reside at the level of potential extravasation sites within the vascular wall." (PMID 26578962, 2015). "While the decrease in tumor growth is mainly attributed to enhanced tumor cell clearance by macrophages under CD47:SIRPα disruption, other studies have noted that alternative mechanisms may explain the antitumor activities of CD47-blocking antibodies." (PMID 26578962, 2015). "Anti-CD47 antibodies may facilitate elimination of tumor cells through a variety of mechanisms." (PMID 26390038, 2015). "Thus, CD47 blocking antibodies may have different effects depending on the type of tumor that it targets." (PMID 26077800, 2015). "However, quantitative imaging highlighted that the CD47-derived peptide could decrease tumor proper volume." (PMID 26046793, 2015). "In addition to directly reducing CD4+ and CD8+ T cells apoptosis, PD-1 blockade may also restore T cell activity by decreasing the CD47 expression in the tumor microenvironment." (PMID 26573233, 2015).
tumor (continued). "In addition, blocking CD47 signaling induced the phagocytosis of tumor cells by macrophages, which suggests that CD47 expression on tumor cells may help tumors to evade immunosurveillance in their hosts." (PMID 26077800, 2015). "Furthermore, CD47 blockade results in a significant increase in tumor phagocytosis by macrophages." (PMID 26093091, 2015). "Therefore, we tested the link between CD47 expression on tumor cell surface and IL-10 induction." (PMID 24073274, 2013). "However, the role of CD47 in response to IR in tumor cells is yet to be determined." (PMID 22891162, 2012). "Both tumor‐derived and RBC‐derived exosomes rely on heparin‐ and integrin‐dependent entry, but only RBC exosomes additionally require CD47, a self‐recognition signal, thereby revealing a distinct uptake pathway." (PMID 41159542, 2026). "We demonstrate that the anti-CD47 antibodies SRF231, magrolimab, and B6H12 eliminated tumor cells from various in vitro and in vivo lymphoid malignant models via the activation of the RIPK1/MLKL/necroptotic pathway." (PMID 41484790, 2026). "Immune markers, such as CD47, CD163, and B7-H3, play crucial roles in tumor immune evasion and macrophage polarization." (PMID 42075550, 2026). "Changes in these genes can control how the tumour interacts with the immune system and influence the expression of immune checkpoint molecules such as PD-1, PD-L1, PD-L2, CTLA-4 and CD47." (PMID 41834250, 2026). "This platform leverages localized viral delivery to selectively downregulate "don't eat me" signals (CD47 and CD24) on tumor cells, thereby restoring macrophage phagocytic capacity." (PMID 42003796, 2026). "Here, we constructed hypoxia response bacteria (HRB) that specifically expressed CD47 antibody (aCD47) under hypoxic conditions in the TME, enabling the in situ synthesis of ICIs at the tumor site." (PMID 41709777, 2026). "Immunohistochemical testing determined SIRPα expression in peritumoral immune infiltrates and CD47 expression in tumor and immune cells, while tumor proportion score (TPS) and combined positive score (CPS) were used to evaluate CD47 staining." (PMID 40926176, 2026). "As the most studied anti-phagocytic signal in the tumour microenvironment (TME), CD47 has been shown to be overexpressed on the surface of multiple types of cancer cells." (PMID 41438583, 2026). "DNAJC13 emerged as the top hit across all three murine tumor models (B16, MC38, EMT6), suggesting a robust and lineage-independent role in modulating CD47 levels." (PMID 41601654, 2026). "Subcutaneous tumors were established using the three cell lines, and tumor growth was monitored in mice bearing vector control, DNAJC13 knockout, and CD47 knockout tumors." (PMID 41601654, 2026). "In combination with anti-CD47 therapy, MCT-NE#9 substantially reduced tumor growth (up to 3.37-fold), induced sustained ferroptosis, and promoted macrophage-mediated antitumor immune responses." (PMID 41510171, 2026). "Studies above have demonstrated that MMW irradiation can down-regulate the levels of CD47, CD38, and TGF-β in the tumor microenvironment." (PMID 41383334, 2025). "IMM2902, a novel bispecific antibody, simultaneously targets CD47 and HER2, significantly enhancing anti-tumor immune responses by blocking the CD47/SIRPα signaling pathway and activating immune cell phagocytosis." (PMID 40867511, 2025). "Blocking the interaction of CD47 with SIRPα reduces Src homology region 2 domain-containing phosphatase 1 (SHP-1) and SHP-2 activation, restoring the anti-tumor activities of APCs." (PMID 41322194, 2025). "CD47 nanobody or IR700@Nb289‐OMVs plus NIR irradiation alone slightly inhibited metastatic lung and abdominal tumours, and extended survival, but all mice succumbed due to the high tumour burden at the end of the experiment." (PMID 40240911, 2025). "Two antiphagocytic (“don't eat me”) signals that allow tumor immune evasion have been discovered, including CD24 and CD47." (PMID 41354057, 2025).
tumor (continued). "Co-administering CD47E-CAR T-cells and a CD47-blocking mAb thereby protected the CAR T-cells from macrophage-mediated phagocytosis, whilst unleashing phagocytosis against tumor cells." (PMID 41019052, 2025). "However, the mechanism of CD47 ubiquitination on tumor immune escape remains unclear." (PMID 39665172, 2025). "Combining CD47/SIRPα-targeted treatments with other therapeutic modalities, including angiogenesis inhibitors and ICIS, can further suppress tumor progression." (PMID 40607438, 2025). "Blockade of CD47 enabled M1 TAMs to be enriched in the TME and produce greater tumor-phagocytosing effects." (PMID 40850976, 2025). "Further studies should examine the expressions of CD47 and CD24 at the transcriptional levels to further understand the mechanism of CD47/SIRPα and CD24/Siglec‐1 pathways in the anti‐tumor immune response." (PMID 41354057, 2025). "Knockdown of TUG1 can inhibit tumor growth and metastasis, increase the infiltration of CD8+ T cells and M1 macrophages in the tumor, and activate CD8+ T cells through PD-L1 while enhancing macrophage phagocytosis through CD47." (PMID 40352941, 2025). "To augment the anti-tumor function of CAR-NK cells, we combine a high-affinity CD47 blocker, CV123, with CDH17-targeting CAR-NK cells." (PMID 40487639, 2025). "Macrophage-based therapies represent a novel frontier in cellular immunotherapy for PROC, with CAR-M, CD47 blockade, and CSF1R inhibition offering complementary strategies to reprogram or enhance macrophage anti-tumor activity." (PMID 40643516, 2025). "TAMs, often characterized by a high expression of CD47 and CD163, contribute to immune evasion and tumor progression." (PMID 39857116, 2025). "Targeting CD47 in combination with an ICI reactivates TAM-M1 and T cell functions, possibly generating tumor growth reduction." (PMID 41562047, 2025). "All three treatment groups, except for PBS, exhibited reduced tumor burden to varying degrees, the C + o treatment group demonstrated superior tumor regression and survival benefits compared to oAd-CD47 group and CAR-Ms group in the CT26 tumor model." (PMID 40814015, 2025). "As shown by Western blotting, the protein level of CD47 in the DMPLAC/siCD47 group was notably reduced, indicating that DMPLAC successfully and efficiently delivered CD47 siRNA into tumor cells and enabled it to exert its function." (PMID 40006507, 2025). "Alternatively, directly targeting phagocytosis-inhibitory pathways, including the CD47–SIRPα axis, or activating innate sensing pathways through TLR or STING agonists, offers promising avenues for enhancing macrophage-mediated tumor clearance." (PMID 40724825, 2025). "This novel combination immunotherapy of NDV and CD47 ICIs leverages the induction of a proinflammatory tumor microenvironment and recruitment of anti-tumor immune cells by NDV, with increased phagocytosis and antigen presentation mediated by CD47 blockade." (PMID 41322194, 2025). "Phagocytosis of dying tumor cells is stimulated by “eat me” signals, in which CRT plays a preponderant role, whereas this process is inhibited by “don’t eat me” CD47 signals." (PMID 40429961, 2025). "By using anti-CD47 antibodies to block the CD47-SIRP α pathway, it mediates cell phagocytosis and targets tumor cells, providing a new therapeutic strategy for treating human malignant tumors." (PMID 40124370, 2025). "The third-generation CD47-SIRPα inhibitor HCB101 significantly inhibits tumor growth as monotherapy and demonstrates synergistic anti-tumor effects with anti-HER2 or anti-EGFR monoclonal antibodies." (PMID 41417432, 2025). "To evaluate CD47 expression and TAM biology within various tumor molecular subtypes, we used the tumor sample transcriptome to stratify samples into known molecular subtypes for CRC, HNSCC and BC." (PMID 41415295, 2025).
tumor (continued). "Collectively, these results demonstrate that engineered OMV‐mediated photoimmunotherapy combined with CD47 nanobodies holds enormous potential to suppress primary and metastatic CDH17‐positive CRC and promote complete tumour eradication." (PMID 40240911, 2025). "We found that CSCs expressed high levels of tumor stemness genes (PROM1, CD24, CD47, ANPEP, ALDH1A1, OLFM4, and SOX9), and demonstrated a high cancer stemness score, along with activation of the cancer driver genes EGFR and ERBB2." (PMID 39950944, 2025). "CD47 acts as a “don't eat me” signal, and its blockade enhances macrophage activation (CD69+) and phagocytosis against tumor cells." (PMID 40487639, 2025). "The results indicated that, compared to untreated animals, the tumor growth rate was slower in the NIR‐PIT group using CD47‐Alexa Fluor 790 (CD47‐AF790), allowing for more sustained tumor control." (PMID 40385528, 2025). "After the tumor was established, the mice were randomly assigned into four groups and treated with PBS, CAR-Ms alone, oAd-CD47alone, and CAR-Ms combined with oAd-CD47 (C + o)." (PMID 40814015, 2025). "Due to limited tumor tissue availability, baseline EGFR, CD47, and PD-L1 expression were uninformative." (PMID 41171165, 2025). "NONO knockdown significantly downregulated the core clock gene PER2 and the oncogene DEC1 and markedly reduced tumor-cell expression of key fibroblast-signal receptors, including ITGB1, SDC1, and CD47." (PMID 41174721, 2025). "CD47‐positive GBM cells display features of cancer stem cells, reinforcing their role in tumour aggressiveness and immune escape." (PMID 41195773, 2025). "Combining CD47 inhibition with pro-phagocytic “eat-me” signals, such as calreticulin (CALR), can amplify macrophage-mediated clearance of tumor cells." (PMID 41179296, 2025). "Given the central role of macrophages in the TME and their impact on tumour progression, the interplay between IL-8/CXCR2 signalling, CD47 regulation, and macrophage infiltration holds significant clinical relevance." (PMID 41163221, 2025). "Mechanistically, TUG1 acts as a miRNA sponge for miR-141 and miR-340 to regulate PD-L1 and CD47 expression and interacts with YBX1 to transcriptionally upregulate both immune checkpoint molecules, thereby modulating tumor immune escape." (PMID 41346602, 2025). "For instance, using SIRP1α-CD47 inhibitors and anti-MS4A4A antibodies, certain unique TAM subpopulations can be utilized to impede tumor growth or restore T cell-mediated anti-tumor immunity." (PMID 40191203, 2025). "This limited activity likely reflects redundancy within the tumor microenvironment (TME), where alternative immune-evasion pathways compensate for CD47 blockade." (PMID 41179296, 2025). "Studies suggest that inhibiting the expression of CD47 on tumor cell surfaces or the C-C chemokine receptor type 5 (CCR5) receptor on microglia in GB can increase the ratio of M1/M2-TAMs and improve tumor phagocytosis." (PMID 40061139, 2025). "For these tumor sizes and RT doses, immunogenic cell death values (I=(1−S)A) remain zero or negligible compared to ICD values when the SIRPα-CD47 pathway is disrupted." (PMID 41296731, 2025). "In HCC models, the anti-CD47 antibody B6H12 stimulates macrophage-mediated clearance, restrains tumor growth, and increases chemotherapy efficacy." (PMID 41488615, 2025). "A recent study has shown that the in vivo blockade of CD47/SIRPα, in addition to an ICD inducer, resulted in increased survival and a reduction in tumor size." (PMID 40356923, 2025). "CD47’s established role in tumor immune evasion may represent a targetable vulnerability in personalized therapeutic approaches and has prompted the development of an anti-CD47 monoclonal antibody, which blocks the CD47-SIRPα interaction to promote phagocytosis of tumor cells." (PMID 41295262, 2025). "In conclusion, a CD47 IHC assay was developed and CD47 expression and prevalence patterns were quantified in HNSCC, BC and CRC tumor samples." (PMID 41415295, 2025).